MAX (MYC associated transcriptional regulator X)
Diseases named in the same sentence as MAX in open-access papers (continued):
Sharing a sentence is not in itself a finding about the gene and the disease.
cancer (continued). "These include known factors such as IDH1, as well as previously unreported genes, including four cancer driver genes (FGFR3, PPP6C, MAX, GNAQ)." (PMID 34944895, 2021). "The MYC/MAX/MAD network is a key axis in the cell decision-making for differentiation and proliferation, and it is altered in several types of cancer." (PMID 24349289, 2013). "MAX, a core component of the MYC/MAX/MAD network, forms heterodimers with MYC or MAD proteins to regulate genes involved in cell proliferation, differentiation, and metabolic reprogramming, particularly in cancer and inflammatory diseases." (PMID 41614919, 2026). "Based on the in silico prediction models, SPR data and competitive inhibition shown by ELISA, we suggest that rLon and its domains inhibit MYC/MAX complex formation, which would explain the potent inhibition of MYC-dependent gene expression in rLon-treated mice with cancer or infection." (PMID 40000737, 2025). "Furthermore, the analysis of MAX, DHX29, and TAPBP mRNA in pre-treatment and on-treatment analyses of pan-cancer patients treated with anti-PD1 therapy exhibited predictive value in discriminating PFS." (PMID 38513890, 2024). "Moreover, MBZ can modulate various cancer-associated pathways, including MAPK14, MEK-ERK, C-MYC, USP5/c-Maf, TNIK, XIAP, ELK/SRF, NFKB, MYC/MAX, E2F/DP1, TGF/SMAD, AP1, and STAT1/2, dependent on the specific cancer model." (PMID 36674870, 2023). "Kynurenic acid seems to be the hub in the metabolite/gene cancer correlation network inferred from CCLE, and several of the cancer genes significantly correlated with metabolites include pan-cancer actors such as MAX, ATM, PTEN, and BRAF." (PMID 35409231, 2022). "As the oncogenic function of LINC00958 has been reported in multiple cancer types, MYC/MAX, a vital oncogenic transcription factor in various cancers, may contribute to the transcriptional regulation of LINC00958 in cancer." (PMID 35223488, 2022). "This study suggested that miR-22, as a cancer suppressor, participates in CRC progression by targeting MAX, which might provide basic information for therapeutic targets for CRC." (PMID 36061355, 2022). "Concerning transcription factors, sets of the most important features are less similar to each other for different cancer types but nevertheless CTCF, GABPA, RXRA, SP1, MAX and NR2F2 are more frequently included in top features than other transcription factors." (PMID 33647036, 2021). "Pathways derived from NOTCH3, PARD3, CACNA1A, MAX, RAD50, FUS and LMO2 were cancer-related." (PMID 34540367, 2021). "For example, we suppose that retinoid receptors, MAX and GATA3, as demonstrated in other types of cancer, could interact with the zinc finger protein YY1 that is known to modify chromatin structure and interact with insulators elements such as CTCF." (PMID 34449674, 2021). "We report here that MAX operates as an unexpected integral regulator of the circadian transcriptional network in an MYC-independent manner in both cancer and non-cancerous cell lines." (PMID 32225100, 2020). "Our knockdown experiments indicate that MAX regulates the transcription of diverse genes belonging to the core clock machinery in both cancer and non-cancerous cell lines." (PMID 32225100, 2020).
cancer (continued). "The mechanisms by which MYC functions without its dimerization partner MAX, particularly in the context of cancer, remain to be elucidated, but does suggest that there are additional means of activating the MYC transcriptional program." (PMID 28587062, 2017). "Thus, the MYC/MAX/MNT system that drives cell growth and proliferation is robustly set to an off state during normal homeostasis, whereas in cancer, the system is locked to a pathological on state." (PMID 28583252, 2017). "MYC Associated Factor X (MAX) plays a key role in the MYC-MAX-MAD gene regulatory network; however, its direct involvement in cancer has not yet been reported." (PMID 27294413, 2016). "Moreover, numerous examples of cancer-relevant genes affected at the splicing level (e.g. ANXA7, GLI1, MAX, KLF6) have been reported in GBM." (PMID 27287018, 2016). "Studies have shown that many malignant tumors have over-expressed MYC and under-expressed MAX." (PMID 26046465, 2015). "Because of the weak oscillation displayed by MDA-MB-231 cancer cells, we thus decided to evaluate whether MAX could control clock gene transcription in two non-cancerous human cell lines, foreskin fibroblast BJ-5ta and epithelial MCF10A." (PMID 32225100, 2020). "Our findings that Omomyc is able to modulate the MYC/MAX ratio in cancer cells suggest that Omomyc may affect MYC/MAX-dependent transcription by binding to chromatin as homodimers that largely displace MYC from DNA and can compromise DNA binding of MAX/MAX complexes as well." (PMID 36830948, 2023).
infection (9 papers, 2015 to 2025). The state of being infected such as from the introduction of a foreign agent such as serum, vaccine, antigenic substance or organism. "Making use of AlphaFold2, Yan and colleagues show that structurally conserved effectors, including the MAX effector family, from M. oryzae are temporally co-expressed during the infection process." (PMID 38411527, 2024). "Expression profiling showed that the MAX effector repertoire was induced specifically and massively during infection." (PMID 37695773, 2023). "Like the Bas3 gene, encoding a P. oryzae effector specifically induced during the biotrophic phase of infection, all MAX genes showed maximal expression between the second and fourth day post-inoculation." (PMID 37695773, 2023). "64% of the MAX genes (42 genes) showed an infection-specific expression profile with relative expression levels ranging from very low (0.008–0.04) to very high (>5)." (PMID 37695773, 2023). "MAX effectors are massively expressed during the biotrophic phase of infection, suggesting an important role in disease development and fungal virulence." (PMID 37695773, 2023). "The expression of MAX effector genes was primarily restricted to the early biotrophic phase of infection and strongly influenced by the host plant." (PMID 37695773, 2023). "We showed that the expression of MAX effector genes is largely restricted to the early biotrophic phase of infection and strongly influenced by the host plant." (PMID 37695773, 2023). "Depending on the host genotype, between 64 and 78% of the MAX effectors were expressed and expression was particularly strong during the early stages of infection." (PMID 37695773, 2023). "During Kitaake infection, 78% of the MAX genes (52 genes) were upregulated compared to the in vitro condition, while 64% (43 genes) were induced upon infection of Maratelli." (PMID 37695773, 2023). "As expected, infection with MAX-overexpression siRNA resistance lentivirus rescued the decreased IGFBP1 level on MAX knockdown." (PMID 35146559, 2022). "Expression profiling indicated that the majority of the M. oryzae MAX-effector candidates are expressed during early infection." (PMID 26506000, 2015). "Expression analysis indicated that the majority of M. oryzae MAX-effectors are expressed specifically during early infection suggesting important functions during biotrophic host colonization." (PMID 26506000, 2015). "The expression pattern of all these genes and of 3 genes coding for MAX-effectors identified only by Psi-Blast searches was clearly different from the markers of very early or late infection (Orf3 and MGG01147, respectively)." (PMID 26506000, 2015). "To test whether the genotype of the host plant could influence the expression of MAX genes, we analyzed their expression patterns upon infection of the rice cultivar Kitaake, which has a higher basal resistance to P. oryzae than Maratelli." (PMID 37695773, 2023). "Therefore, the majority of the MAX-effector candidates seems specifically expressed during biotrophic infection and can therefore be considered as potential virulence effectors." (PMID 26506000, 2015). "It will be interesting to determine in the future whether MAX effectors play similar roles in these early infection processes in both groups of fungi." (PMID 26506000, 2015). "Only in M. oryzae and M. grisea that are both from the genus Pyricularia huge numbers of MAX-effector candidates were detected and expression profiling confirmed that most of them are likely bona fide effectors expressed specifically during biotrophic early infection." (PMID 26506000, 2015). "Indeed, the loss of MAX effectors in specific lineages of P. oryzae could primarily serve to escape from non-host resistance during infections of novel plant species carrying immune receptors specifically recognizing these effectors." (PMID 37695773, 2023).
infection (continued). "Interestingly, the expression of PRRs, MAPK signaling pathway genes (MyD88, AP-1, c-fos, Jun, JunD, MAX, and c-Myc), cytokines, chemokines, IFNs, and IFN-stimulated genes were increased after infection in resistant chickens." (PMID 34991196, 2022). "Such a high degree of functional redundancy, along with the HMA-binding previously demonstrated for the MAX-effectors AVR-Pik, AVR1-CO39 and AVR-Pia, further indicates that targeting HMA proteins is an important virulence activity during host infection by the blast fungus." (PMID 34758051, 2021). "As expected, infection with OSR2-overexpression lentivirus, rather than control virus, at least partly rescued the downregulated IGFBP1 expression level upon MAX knockdown." (PMID 35146559, 2022).
adenocarcinoma (2 papers, 2008 to 2021). A common cancer characterized by the presence of malignant glandular cells. "Adenocarcinoma sections displayed MAX immunoreactivity localised to both nuclei and cytoplasm." (PMID 18493233, 2008). "The aims of this work were to characterise the expression of c-MYC, MAX and the MAD family in adenocarcinoma development and assess the effects of overexpression on cellular behaviour." (PMID 18493233, 2008).
genetic disorder (1 paper, 2023). "Among the familial cases, MEN2 was the most common genetic disorder, affecting 23% of the sample, with a further 4 cases associated with NF1, MAX, and SDHB pathological variants." (PMID 36896586, 2023).
hematological malignancies (1 paper, 2016). "Accumulation of mutations play a key role in the aging process, and it was shown that mutation of MAX is associated with hereditary pheochromocytoma, whereas mutation of MYD88 was found to be associated with many hematological malignancies." (PMID 26895224, 2016).
MAX also shares sentences with these, for which no sentence is quoted: bladder cancer (3 papers); acute promyelocytic leukemia (2); Burkitt lymphoma (2); ganglioneuroblastoma (2); glioblastoma (2); head and neck paraganglioma (2); hyperparathyroidism (2); lung adenocarcinoma (2); peripheral T cell lymphoma (2); respiratory diseases (2); schizophrenia (2); Von Hippel Lindau syndrome (2); abortion (1); acute leukemia (1); adenoma (1); adrenocortical adenoma (1); adult T-cell leukemia (1); angioimmunoblastic T-cell lymphoma (1); arthropathy (1); asthma (1); B-cell lymphoma (1); bacterial infection (1); Bloom syndrome (1); breast tumors (1); colitis (1); cutaneous T-cell lymphoma (1); diabetic nephropathy (1); endocrine tumors (1); endometrioid carcinoma (1); gastrointestinal tumor (1).
A further 18 diseases each share a sentence with MAX in 1 paper.